TNF (tumor necrosis factor)
Diseases named in the same sentence as TNF in open-access papers (continued):
Sharing a sentence is not in itself a finding about the gene and the disease.
melanoma (continued). "Moreover, GP-B1 not only significantly inhibited the growth of cancer cells, but also improved cellular immune response by increasing levels of tumor necrosis factor-α (TNF-α), interferon-γ (IFN-γ), interleukin-10 (IL-10) and interleukin-12 (IL-12) observed in the serum of melanoma-B16-bearing mice." (PMID 27708693, 2016). "Although the role of MCP-1 in NHM biology is not known, MCP-1 potentiates tumor necrosis factor-α (TNF-α) and IL-1α in the stroma, and may potentiate early tumor growth and tumor angiogenesis in malignant melanoma." (PMID 27314341, 2016). "In addition, we identify five genes (ALG12, GUSB, RPLP0, KRBA2, and ADAT2) that are stably expressed in melanoma cells independent of the presence of T cells or the T cell-derived cytokines IFNγ and TNFα." (PMID 27625650, 2016). "In summary, these results reveal a novel TNFα/NF-κB/CD271 axis whose activation contributes to the acquisition of resistance to BRAFi and therefore may represent a novel therapeutic target to improve the efficacy of therapy in melanoma." (PMID 27462428, 2015). "We hypothesized that prolonged TNF-α exposure (72 h) steadily increases c-JUN mRNA and protein expression through reduction of MITF and thereby progressively amplifies inflammatory gene programmes in melanoma cells." (PMID 26530832, 2015). "Furthermore, when IL-1β and TNF-α were used at a non-toxic level, they enhanced peritoneal lymph node colonization by melanoma cells." (PMID 25120672, 2014). "In conclusion, we determined that transient TNF suppresses the PI3K/AKT-mediated melanoma SC differentiation and enlarges a GFPhigh melanosphere-initiating CSC subpopulation that preserves the TNF-instigated changes, reinforcing their post-TNF capacity to form tumor-like melanospheres." (PMID 25223735, 2014). "However, TNF-α treatment was not able to stimulate MCP-1 expression in melanoma cells pre-treated with COX-2 siRNA." (PMID 23420676, 2013). "Interestingly, the antitumor activity induced by a recently discovered iNKT agonist, β-mannosyl-ceramide (β-ManCer), in mice bearing the CT26 colon carcinoma or B16F10 melanomas was mediated primarily by nitric oxide species (NOS) and tumor necrosis factor alpha (TNF-α)." (PMID 23118781, 2012). "The majority of melanoma-infiltrating γδ cells showed effector memory and terminally-differentiated phenotypes and, accordingly, polyclonal γδ T cell lines obtained from tumor-infiltrating immune cells produced IFN-γ and TNF-α and were capable of killing melanoma cell lines in vitro." (PMID 23189169, 2012). "TNFα and VEGF secretion increased in the supernatant of LPS-treated BMSCs; however, anti-VEGF neutralizing antibodies added to B16M and A375M cells prior to LPS-treated BMSC-CM resulted in a complete abrogation of both adhesion- and proliferation-stimulating effect of BMSC on melanoma cells." (PMID 21867538, 2011). "However, in this study the authors used a single HLA-A*0201 negative allogeneic melanoma cell line killed after a combination of TNF treatment, γ irradiation and culture in serum-free medium, plus the addition of CD40L to activate DCs." (PMID 17448240, 2007). "In addition, α-MSH blocked the response to TNF-α for the HBL melanoma cells but not the C8161 line, and is therefore consistent with an anti-inflammatory action of this molecule." (PMID 15054471, 2004). "We found that immunisation of C57BL/6 mice with TNF autovaccine produces a 100-fold antibody response to TNF compared to immunisation with phosphate-buffered saline vehicle control and significantly reduces both the number (P<0.01) and size of metastases (P<0.01) of B16F10 melanoma cells." (PMID 15026813, 2004). "Our group has showed that α-MSH can inhibit tumour necrosis factor-α (TNF-α)-induced upregulation of intercellular adhesion molecule-1 (ICAM-1) in human melanocytes and melanoma cells and reduce interactions between cytokine-stimulated melanoma cells and T lymphocytes." (PMID 14612916, 2003).
melanoma (continued). "To measure noninvasively whether cell surface bound proteolytic activity was modified by TNF-α, we also added BODIPY® casein directly to the HBL melanoma cell culture medium during the period of cell invasion through the fibronectin monolayer in the invasion assay." (PMID 12966436, 2003). "Similarly, the general proteolytic activity expressed in the cell conditioned medium and by the melanoma cells themselves was not upregulated in response to preincubation with a wide range of concentrations of TNF-α." (PMID 12966436, 2003). "Fas-Lribozyme did not affect the expressions of Fas and TNF-α in melanoma cells." (PMID 12177809, 2002). "Tumour necrosis factor-alpha (TNF-alpha) reduced the interstitial fluid pressure (IFP) to 54-64% (P < 0.05) and the mean arterial blood pressure (MABP) to 70% (P < 0.01) of control values after 5 h in three human melanoma tumour lines transplanted to nude mice." (PMID 8761366, 1996). "However, clustered examination of the transcriptome data identified three pathways (TNF signaling, apoptosis, and pathways regulating pluripotency of stem cells) that were equally influenced in the four BMMC lines, thereby underscoring the therapeutic potential across various melanoma subtypes." (PMID 40285526, 2025). "Thus, NK cluster 01 subtype cells have the greatest potential for regulating CM malignant cells through the tumor necrosis factor (TNF)–TNFRSF1B axis, suggesting that NK cluster 01 cells may respond to melanoma cells by producing proinflammatory cytokines, including IFNγ and TNF." (PMID 41357561, 2025). "Similarly, Pozniak and colleagues showed that overexpression of TCF4 leads to decreases in TNF-α and T cell activation and suppression of TCF4 elicits inflammation, including increases in IFNs, thereby increasing the sensitivity of immune checkpoint inhibitors used to treat melanoma." (PMID 38470486, 2024). "Moreover, as MDM2 inhibitors are already available for clinical use, we propose to test them in a clinical trial to assess whether or not their administration would improve the results of TNF-based ILP in patients with in-transit melanoma metastasis." (PMID 38138884, 2023). "Interestingly, TNF-α signalling via the NF-κB pathway was significantly downregulated with a reduction ranging from 7- to 40-fold in expression of some of its prooncogenic target genes (e.g., JUNB, FOS, DUSP1) and melanoma-related genes (e.g., EGR3, NR4A3, CCN1)." (PMID 34497073, 2021). "In human melanoma cell lines, TNFα and INFγ could not induce H3K27me3 expression." (PMID 32041674, 2020). "Therefore, monocytes from melanoma progressively acquire a CD14+/HLA-DR-/low suppressive phenotype that alters T-cell proliferation and interferon-γ production while enhancing the secretion of inhibitory cytokines such as IL-6, TNF-α and TGF-β within the tumor milieu." (PMID 29755693, 2018). "High dose TNFα has been used to treat solid tumors, but due to many side effects upon systemic administration the success rate has been rather low, and strategies to administer this cytokine more locally had been developed for e.g. melanoma patients, but have not been used to treat RCC." (PMID 24885059, 2014). "Thus, in the present study, macrophagic IL-1β and TNF-α were observed to promote VEGF-C expression in TAMs, as well as melanoma lymph node metastasis, suggesting that inhibiting the signaling between tumor cells and TAMs may be required to inhibit lymphangiogenesis and lymph node metastasis." (PMID 25120672, 2014). "The production of tumor necrosis factor (TNF) and interferon gamma (IFNγ) in TEX cells upon MCT11-blockade did not improve in the poorly responding melanoma model." (PMID 40114716, 2025). "Moreover, CY12-RP2 could inhibit melanoma lung metastasis, and abrogated the immunosuppressive effects of PDPN by increasing the proportion of CD3 + CD4 + T cells, CD3 + CD8 + T cells, CD49b + Granzyme B + NK cells, and CD11b + CD86 + M1-like macrophages and the levels of IL-1β, TNF-α, and IFN-γ." (PMID 38167452, 2024).
melanoma (continued). "ELISA assay confirms that MLiM, but not other types of melanoma organ‐metastasis such as MLNM or MBM, secretes enhanced levels of TNF‐α." (PMID 39496484, 2024). "Most secreted factors (TNFα, GM-CSF, G-CSF, PDGF-BB, CCL5, CCL11, IL-3, IL-6) were not induced by exogenous IFNγ in our panel of melanoma cells, confirming the complex inflammatory signaling profile of de-differentiated PD1 PROGs with intrinsic IFNγ signaling." (PMID 36934113, 2023). "While serum TNF-α and IFN-γ levels did not change, IL-2 levels were upregulated similarly to those seen in melanoma tissues on the fourth and seventh days after treatment with Ce6-PDT." (PMID 36835310, 2023). "We found that IL-6, IL-8, TNF-α and CCL5 were significantly increased in the plasma of metastatic and non-metastatic melanoma patients as compared to HD." (PMID 36860876, 2023). "Of note, we have also tested the levels of other cytokines (i.e. IL6, TNF-α and IL1β) in THP-1 cells exposed to CM coming from melanoma cells and we have not observed any significant modulation." (PMID 36418472, 2023). "To directly examine how the host TNF signaling affects Ruxo efficacy, we inoculated TNF−/− mice lacking TNF in host cells, including immune cells (T cells, myeloid cells, etc.), with IFNγR1KO melanoma cells, followed by Ruxo treatment." (PMID 36008408, 2022). "Immunoprecipitation of induced GFP-tagged Usp27xL (GFP-IP) confirmed the presence of Usp27x in complex with RIPK1 in WM1158 melanoma cells (the same was seen in 1205Lu cells overexpressing GFP-mUsp27xS, data not shown) independently of TNF treatment." (PMID 35044632, 2022). "The percentages of polyfunctional (IFNγ+TNFα+) total MAIT cells and CD4+ MAIT cells were reduced in melanoma patients compared to HD, while no changes in the production of these cytokines by CD8+ or double‐negative (CD4−CD8−, DN) MAIT cells were observed." (PMID 35028137, 2022). "Melanoma BLM cells were also analyzed after co-culture, showing no expression of CCL20 and low induction of TNF mRNA, whereas VEGFA mRNA was basally expressed by BLM cells." (PMID 34439098, 2021). "Significantly, higher contents of the intracellular cytokines CCL20, TNF, and VEGFA were quantified in TAMs infiltrating metastasizing compared to non-metastasizing skin primary melanomas (p < 0.001)." (PMID 34439098, 2021). "Finally, B16F10 melanoma cells selected for low production of TNF demonstrated increased tumor growth and reduced necrosis in vivo in comparison with cells that did not produce TNF, whereas cells selected for a high TNF production did not have any advantage over control cells." (PMID 33917839, 2021). "NKG2D-CAR T cells exhibited robust CD107a degranulation and intracellular production of TNF-α and IFN-γ when co-cultured with AML and T-ALL lines, but not in response to the murine melanoma cell line B16 (negative for human NKG2D-ligands)." (PMID 33384686, 2020). "Infiltration of human melanoma tumors by CD8+ T cells, which co-express PD-1 and CTLA-4 at high levels and produce IFN-γ efficiently but not TNF, has been proposed as a good predictive marker of anti-PD-1 therapy." (PMID 29273790, 2017). "Following transfection of A375 melanoma cells with PKN1 siRNAs, we found that TNF-dependent NF-κB signaling was not changed relative to siRNAs targeting control sequences." (PMID 24114839, 2013). "We examined the level of cEPCs, vascular endothelial growth factor (VEGF), and angiopoietin-2 in the blood of sarcoma and melanoma patients before and after isolated limb perfusion (ILP) with or without recombinant human tumor necrosis factor-α (rhTNF-α)." (PMID 22948772, 2013). "The inflammation status in B16 melanoma and LLC tumors with and without D6D inhibition was determined by measuring gene expression of the inflammatory cytokines IL-6 and TNF-alpha." (PMID 23112819, 2012).
melanoma (continued). "Supernatant from CD8+ CTL793 after 24–48 hr of stimulation with autologous melanoma cells WM793 contained significant amounts of IFN-γ, TNF-α, and GM-CSF, but not IL-2 or IL-4 (data not shown, except for IFN-γ release in Table II)." (PMID 16281981, 2005). "IFN-γ, TNF-α, and GM-CSF were produced by the CTL, and not by irradiated autologous melanoma cells, since the supernatants derived from the melanoma cells showed no significant cytokine secretion (data not shown)." (PMID 16281981, 2005). "By contrast, in the melanoma TME, TGF-β converted NK cells into noncytotoxic ILC1-like cells, which had an immune-suppressive phenotype that aided in metastasis through the release of TNF-α." (PMID 39126091, 2024). "Dedifferentiated melanoma cells have been reported to secrete multiple cytokines in greater quantity, notably CCL2, CCL5 and IL-1β, either without inflammatory stimuli or when stimulated with TNFα." (PMID 39736644, 2024). "It is known that ICI treatment is associated with increased TNF gene expression, and in agreement with our findings, it has been reported that melanoma patients responding to ICI had higher gene expression of TNF and TNF response signatures after therapy compared to non-responders." (PMID 38067341, 2023). "In addition, Western blot analysis showed that TNF-α and CXCL1 protein were detected in tumor tissues from WT mice injected with B16F10 melanoma but not in those from KLK6−/− mice injected with B16F10 cells." (PMID 36552865, 2022). "IL-7 stimulation to CD8+ T cells from melanoma patients not only enhanced direct cytolytic function of CD8+ T cells to target cells, but also promoted IFN-γ and TNF-α secretion, indicating that IL-7 increased cytolytic and non-cytolytic activity of CD8+ T cells in melanoma patients." (PMID 35850640, 2022). "We also evaluated the protein amount of a set of 12 cytokines and chemokines, including IL-2, IL-4, IL-5, IL-6, IL-10, IL-12, IL-17A, TNF-α, IFN-γ, MCP-1, MIP-1α, and eotaxin in TIF and plasma samples of C57BL6 mice, engrafted or not engrafted with B16 melanoma cells." (PMID 34604232, 2021). "Monitored CSCs-surface markers, associated with stemness, resistance, tumor progression, adhesion, and invasion, were find to be not significantly up- or downregulated and TNFα makes cells only slightly more positive for these markers (CD166 and CD271 in melanoma; CD24 and CD26 in carcinoma)." (PMID 33957885, 2021). "Finally, we noted that no single melanoma cell line showed the TNFα-mediated induction of the HLA-ABC, HLA-DR, PD-L1 and PD-L2 immune markers, even though TNFα signaling was intact in all melanoma cell lines tested." (PMID 34073253, 2021). "In addition, TNFα and IL-12, which are both proinflammatory cytokines of mainly innate immunity, were present in B16F10 melanoma after the combined treatment and not in TS/A carcinoma." (PMID 32204304, 2020). "Similarly, TNFα, dcAMP, and H89 treatments did not consistently affect mRNA expression levels of GM2/GD2 synthase or GM1/GD1b synthase genes in melanoma cells." (PMID 31611597, 2019). "However, in contrast to our previous observations in melanoma cells that showed that vaccinia virus and radiation acted synergistically by modulating JNK/TNFα signaling, we did not see evidence of this effect in prostate cancer cell lines." (PMID 26814609, 2016). "In our experiments using SK37 melanoma cell line, IFN-γ alone or IFN-γ and TNF-α treatment did not induce senescence, but these cytokines induced G2/M arrest, potentially because of the different cancer cell line used or marginal expression of TNF-α receptor on SK37." (PMID 26447332, 2015). "As demonstrated for TNF-mediated necroptosis, RIPK3-expressing A375 or, to a lesser extent, IGR melanoma cells (lower result panel), but not control transduced melanoma cells, were not fully protected from IAP antagonist/CD95L treatment by ZVAD-fmk and Nec-1." (PMID 26355347, 2015).
melanoma (continued). "In line with the negative impact of TNF-α-secreting TAMs, TNF-α has also been suggested to upregulate the alternative checkpoint molecule TIM-3 on lymphocytes in vitro and trigger activation-induced cell death of tumor-infiltrating CD8+ T cells in murine melanoma." (PMID 35493461, 2022). "However, in the melanoma TME, TGFβ converts NK cells into non-cytotoxic ILC1-like cells, characterized by an immune suppressive phenotype and a metastasis-promoting activity mediated by TNFα." (PMID 35173725, 2022). "TNF-α is a negative prognostic factor in surgery and correlates with resistance to chemotherapy, while high tumor levels of TNF-α might be beneficial for the melanoma immunotherapy." (PMID 28278159, 2017). "Based on the analysis of tumor-infiltrating NK cells in mice bearing melanomas, we revealed that CTLA4Ig could significantly promote the cytolytic activity of the infiltrating NK cells in vivo via the up-regulation of NK cell cytotoxicity but not through the production of IFN-γ and TNF-α." (PMID 24349559, 2013).